UBE2C (ubiquitin conjugating enzyme E2 C)
Diseases named in the same sentence as UBE2C in open-access papers (continued):
Sharing a sentence is not in itself a finding about the gene and the disease.
lung cancer (46 papers, 2010 to 2025). A malignant neoplasm involving the lung. "The UBE2C/CDH1/DEPTOR axis forms an oncogene and tumor suppressor cascade regulating autophagy and cell cycle, and UBE2C is a lung cancer target associated with Kras mutations." (PMID 40650277, 2025). "High expression of transcription factors FOXM1, MYBL2, and UBE2C was associated with better survival in colon cancer patients, yet showed the opposite effect in stomach and lung cancers, aligning with our findings." (PMID 39542983, 2024). "In conclusion, SLIT3 deficiency promotes lung cancer onset and progression by modulating UBE2C/WNT signaling." (PMID 39479352, 2024). "In summary, our study showed that UBE2C is a growth-essential gene in lung cancer cells harboring a Kras mutation, and Ube2c is required for lung tumorigenesis induced by KrasG12D." (PMID 36548081, 2023). "Taken together, our study shows that the UBE2C/CDH1/DEPTOR axis forms an oncogene and tumor suppressor cascade that regulates cell cycle progression and autophagy and validates UBE2C an attractive target for lung cancer associated with Kras mutations." (PMID 36548081, 2023). "In a lung cancer cell model, UBE2C-mediated autophagy suppression was associated with growth, survival, and malignant phenotypes." (PMID 36548081, 2023). "We then generated a mouse genetic model to further investigate the causal role of Ube2c in KrasG12D-driven lung cancer development." (PMID 36548081, 2023). "We next investigated possible underlying mechanisms by which UBE2C knockdown suppressed growth and survival of lung cancer cells." (PMID 36548081, 2023). "Taken together, our study identified an E2/E3 pair for DEPTOR ubiquitylation and degradation, and validated UBE2C as a promising target for lung cancer associated with Kras mutations." (PMID 36548081, 2023). "Overexpression of UBE2C was reported as an independent risk factor associated with dismal outcomes in patients with lung cancer." (PMID 36505456, 2022). "Activation of the oncogene UBE2C and repression of autophagy are concurrently underlying the initiation, progression, and metastasis of lung cancer." (PMID 29904125, 2018). "Moreover, an additional E2 enzyme, UBE2C, has been found to facilitate the proliferation and viability of lung carcinoma cells harboring Kras mutations." (PMID 38656363, 2024). "Notably, the KRASG12D mutation can promote the expression of UBE2C to promote cell cycle progression and autophagy in lung cancer, which indicated that UBE2C is an attractive carcinogenic genetic target for lung cancer with KRAS mutations." (PMID 37535572, 2023). "Here we report that UBE2C was indeed essential for growth and survival of lung cancer cells harboring Kras mutations, and UBE2C was required for KrasG12D-induced lung tumorigenesis, since Ube2c deletion significantly inhibited tumor formation and extended the lifespan of mice." (PMID 36548081, 2023). "That validates UBE2C as a potential therapeutic target for lung cancer with KRASG12D mutations." (PMID 37535572, 2023). "Targeting UBE2C, therefore, could be a promising strategy for the treatment of lung cancer associated with Kras mutations." (PMID 36548081, 2023). "Furthermore, several studies have demonstrated that UBE2C acts as an underlying oncogene in lung carcinoma, regulating the cell cycle, proliferation, migration, autophagy and chemoresistance of lung carcinoma cells." (PMID 34257576, 2021). "Activation of the oncogene UBE2C and repression of autophagy are concurrently underlying the initiation, progression, and metastasis of lung cancer and exploration of essential association of UBE2C with autophagy will facilitate the identification of the de novo molecular signaling network in NSCLC." (PMID 29904125, 2018).
lung cancer (continued). "However, the underlying mechanism by which UBE2C suppresses autophagy in lung cancer cells, and whether UBE2C plays an in vivo oncogenic role during lung tumorigenesis, are unknown." (PMID 36548081, 2023). "UBE2C promotes cancer cell proliferation by activating the AKT/mTOR signaling pathway and serves as a novel target in lung cancer associated with Kras mutations." (PMID 39513103, 2024). "Further, the data acquired in this research presented the preliminary proof for SLIT3/UBE2C/WNT signaling pathway on lung cancer development and progression, providing novel insight and strategy in clinical NSCLC treatment." (PMID 39479352, 2024). "In lung cancer tissues, UBE2C, belonging to the E2 ubiquitin-conjugating enzyme family, has been found to have significantly increased expression compared with para-cancerous lung tissues." (PMID 39479352, 2024). "The roles of SLIT3 and UBE2C in the development and progression of lung cancer are still controversial." (PMID 39479352, 2024). "This notion is further supported by the observation that DEPTOR levels were increased in lung cancer cell lines upon UBE2C knockdown, and in lung tumor tissues derived from Ube2c-deleted mice." (PMID 36548081, 2023). "Taken together, our results indicated that by increasing DEPTOR levels, Ube2c deletion inactivated mTORC signaling to inhibit KrasG12D-induced lung tumorigenesis, and suggested that UBE2C could be an effective therapeutic target for management of lung cancer associated with Kras mutation." (PMID 36548081, 2023). "What is the molecular mechanism by which UBE2C acts as a growth-essential and Kras-cooperative gene in lung cancer?" (PMID 36548081, 2023). "We also observed that lung cancer sublines with tropism to the leptomeninges have increased levels of UBE2C in comparison with their parental counterparts." (PMID 37215954, 2023). "Additional functional studies should be performed to validate if the leptomeningeal dissemination driven by high levels of UBE2C is a general feature of cancers from different primary origins, using other BM cancer models, besides breast and lung cancer." (PMID 37215954, 2023). "We first performed an association study using TCGA database containing more than 400 lung cancer cases, and found that overexpression of either UBE2C or UBE2S is correlated with the survival of LUAD patients." (PMID 36548081, 2023). "Recently, it has been shown that dactolisib (PI3K/mTOR inhibitor) effectively treats UBE2C-driven orthotopic mouse xenografts of breast and lung cancer BM." (PMID 37958776, 2023). "Collectively, these results clearly showed that in in vitro cell culture models, UBE2C is essential for growth and survival of lung cancer cells harboring a mutant Kras." (PMID 36548081, 2023). "Importantly, UBE2C is expressed at relatively low levels in many normal tissues, but at high levels in human carcinomas derived from the lung, uterus, bladder, and stomach, and high UBE2C expression is associated with worse overall survival of lung cancer patients." (PMID 36548081, 2023). "In multiple lung cancer cell lines, knockdown of either UBE2C or CDH1 significantly extended the protein half-life of DEPTOR, while ectopic overexpression of UBE2C or CDH1 shortened the protein half-life of DEPTOR." (PMID 36548081, 2023). "The protein levels of TOP2A and UBE2C were low in normal lung tissues, while the levels of these genes were high in lung cancer tissues." (PMID 35178291, 2022).
lung cancer (continued). "In this study, we showed that MALAT1 knockdown blocked the proliferation, colony formation, migration and invasion ability of lung cancer cells through the downregulation of expression levels of UBE2C in a substantial number lung cancer cell." (PMID 34257576, 2021). "In conclusion, knockdown of MALAT1 which is upregulated in lung cancer, inhibited the proliferation, colony formation, migration and invasion abilities of lung cancer by sponging miR-491-5p to downregulate UBE2C expression." (PMID 34257576, 2021). "Our pan-cancer analysis indicated that UBE2C mRNA was decreased in the majority of normal tissues, while UBE2C was significantly elevated in cancer tissues, such as in colon cancer and lung cancer." (PMID 34858987, 2021). "The transfection of the UBE2C gene enhances cell proliferation and invasion in lung cancer cells, and the expression of UBE2C serves as a prognostic gene for lung adenocarcinoma." (PMID 33924823, 2021). "Collectively, these findings suggest that MALAT1 stimulates lung carcinoma progression via the miR-491-5p/UBE2C axis." (PMID 34257576, 2021). "UBE2C (ubiquitin-conjugating enzyme 2C), also known as UBCH10, is upregulated during carcinogenesis and development of various human cancers including lung carcinoma." (PMID 34257576, 2021). "This study aimed to investigate the role of MALAT1 in lung carcinoma progression and the mechanism underlying the role of miR-491-5p in the MALAT1 mediated regulation of UBE2C expression." (PMID 34257576, 2021). "This study explored the ceRNA regulatory mechanism of the MALAT1/miR-491-5p/UBE2C system, providing a potential therapeutic target for lung carcinoma." (PMID 34257576, 2021). "Collectively, MALAT1 downregulation suppressed lung carcinoma progression by regulating the miR-491-5p/UBE2C axis." (PMID 34257576, 2021). "Taken together, we demonstrated that the lncRNA MALAT1 is involved in lung carcinoma development by regulating the expression of miR-491-5p and UBE2C." (PMID 34257576, 2021). "For example, UBE2C is involved in the tumorigenesis of colorectal cancer and non–small cell lung cancer (NSCLC)." (PMID 32899896, 2020). "For lung cancer, a study showed that progression-free survival and poorer OS of NSCLC patients was associated with UBE2C overexpression." (PMID 30369945, 2018). "We found that ALKBH5 is highly expressed in lung cancer cells, and more, Alkbh5 knockout significantly decreased UBE2C expression in NSCLC." (PMID 29904125, 2018). "Given the highlighted significance of UBE2C-autophagy repression axis in lung cancer progression, the efficacious treatments that interfere in those signaling cascades in lung cancer are lacking to date." (PMID 29904125, 2018). "Examining the 120 lung cancer samples, only UBE2C and dual specificity protein phosphatase 1 (DUSP1) had average CVs greater than 1 (1.06 and 1.04, respectively)." (PMID 29761043, 2018). "UBE2C protein level was also significantly upregulated in all listed lung cancer cell lines (95-D, A549, H1299, Calu-6, H520, and PC-9) than normal cell line (HBEC)." (PMID 29904125, 2018). "Here we explored the existing status of autophagy and its upstream regulators in NSCLC and found that the depression of autophagy via downregulating UBE2C arrested the malignant phenotypic progression in lung cancer cells." (PMID 29904125, 2018). "These unanswered questions highlight the significance to further explore the dysregulation of UBE2C and its subsequent phenotypic repression of autophagy in lung cancer." (PMID 29904125, 2018). "Comprehensive molecular dissection of deregulated UBE2C-autophagy repression axis in NSCLC will render more possibilities in spotting novel molecular therapeutic targets in lung cancer." (PMID 29904125, 2018). "UBE2C, a ubiquitin conjugating enzyme, is important for lung cancer cell survival and was previously shown by our group to increase in expression progressively in lung lesions." (PMID 20686609, 2010).
lung cancer (continued). "The role of UBE2C is to promote proliferation and inhibit autophagy in lung cancer cells." (PMID 38370368, 2024). "Research has indicated that UBE2C may facilitate the occurrence and progression of KrasG12D lung cancer, and may become a new target for KrasG12D lung cancer." (PMID 38556560, 2024). "Consistent with our finding, previous studies reported that the UBE2C mRNA expression was higher in various cancers including hepatocellular, esophageal squamous cell, adrenocortical carcinoma, gastric, breast, and lung cancers." (PMID 38577722, 2024). "The growth suppression by UBE2C knockdown could be largely rescued by simultaneous DEPTOR knockdown in lung cancer cells." (PMID 36548081, 2023). "Consistently, the tumor suppression by Ube2c KO in the KrasG12D lung cancer model could be largely abrogated by simultaneous Deptor KO, indicating a causal relationship between UBE2C and DEPTOR." (PMID 36548081, 2023). "By using the expression pattern of signature genes identifying the N1 state (Tnf, Fas), the N2 state (Arg1, Ccl2), and immature neutrophils (Stmn1, Ube2c), pseudotime analysis confirmed the developmental direction of TANs with N2 as an early state of TANs in the lung cancer TME." (PMID 37002229, 2023). "Our study is consistent with a previous cell culture–based study, reporting that UBE2C suppressed autophagy in lung cancer cells via an unknown mechanism." (PMID 36548081, 2023). "Deptor KO rescues the phenotypes induced by Ube2c KO in the KrasG12D lung cancer model." (PMID 36548081, 2023). "Ectopic overexpression of UBE2C promoted the growth of lung cancer cells." (PMID 36548081, 2023). "UBE2C was identified as an independent prognostic factor associated with primary tumor size, lymph node metastases, Tumor/Node/Metastasis (TNM) stage, overall survival, and disease-free survival in lung cancer patients." (PMID 37958776, 2023). "UBE2C overexpression increases migration and invasion of breast and lung cancer cells." (PMID 37958776, 2023). "Mounting evidence has shown that UBE2C was upregulated in cancers such as brain cancer, breast cancer, cervical cancer, colorectal cancer, esophageal cancer, hepatocellular cancer, lung cancer, ovarian cancer, and prostate cancer." (PMID 34858987, 2021). "UBE2C has been described as a molecular marker for human lung cancer and liver cancer prognosis, while another study indicated that UBE2C could be a potential biomarker for tumorigenesis and prognosis in squamous cell carcinoma of the tongue." (PMID 34858987, 2021). "Finally, splicing abnormalities of UBE2 genes were common in lung carcinomas and UBE2C was found among the most overexpressed transcripts." (PMID 32664474, 2020). "Indeed, the overexpression of UBE2C was previously reported in hepatocellular carcinoma, thyroid, colon, breast, and lung cancer and our data confirmed this upregulation." (PMID 31067633, 2019). "All our accumulated data suggest the UBE2C-repression of autophagy axis is one of pivotal aberrant activated signaling cascade in NSCLC which is an unavoidable molecular chains worthy of targeting in lung cancer." (PMID 29904125, 2018). "UBE2C has been found to be overexpressed in esophageal squamous cell carcinoma playing a role in cancer progression 13, 14, as well as, in other tumor types such as nonsmall cell lung cancer." (PMID 29575713, 2018). "To profile the activated UBE2C in human lung cancer tissues with assays from RT-PCR and immunoblotting, we found that endogenous mRNA levels and protein expression of UBE2C are significantly elevated in all seven human lung cancers relative to paired normal lung tissues." (PMID 29904125, 2018). "Here, depletion of UBE2C by siRNA was performed to examine whether UBE2C specifically instigates the progression and metastasis of lung cancer cells." (PMID 29904125, 2018).
lung cancer (continued). "Previous studies have reported overexpression of UBE2C in some cancers such as colorectal carcinoma, pancreatic carcinoma, cervical cancer, bladder carcinoma, esophageal squamous cell carcinoma and lung cancer, etc.." (PMID 29021715, 2017). "Furthermore, the possible mechanisms by which SLIT3 might regulate lung cancer development by influencing the UBE2C expression and activating the Wnt signaling pathway activation in lung cancer cell lines were examined." (PMID 39479352, 2024). "Given that DEPTOR knockdown rescued the phenotypes induced by UBE2C knockdown in in vitro cell culture models, we then determined in vivo whether Deptor KO could rescue the suppression of lung tumorigenesis by Ube2c KO in the KrasG12D mouse lung cancer model." (PMID 36548081, 2023). "However, the association study did not reveal the cause or consequence of UBE2C/UBE2S overexpression in lung cancer development." (PMID 36548081, 2023). "Thus, Ube2C is essential for the growth of lung cancer cells." (PMID 36548081, 2023). "Therefore, we hypothesized that MALAT1 may act as a ceRNA to modulate UBE2C expression in regulating lung carcinoma progression." (PMID 34257576, 2021). "We speculated that UBE2C is involved in lung carcinoma progression, which is regulated by MALAT1." (PMID 34257576, 2021). "Hence, we hypothesized that MALAT1 might act as a ceRNA for sponging miR-491-5p and controlling UBE2C expression to regulate the progression in a substantial number lung carcinoma." (PMID 34257576, 2021). "We asked whether autophagy repression is indispensable in UBE2C-induced lung cancer progression." (PMID 29904125, 2018). "Upregulated UBE2C exerts a synergistic efficacy with downregulated SLIT3 and is crucial in lung cancer progression." (PMID 39479352, 2024). "A strong relationship between the upregulation of UBE2C and poor prognoses, such as RFS, distant metastasis-free survival (DMFS), PPS, OS, and FP, was also observed in BRCA and lung cancer." (PMID 35804892, 2022). "The results of this study showed that MALAT1 knockdown decreased UBE2C expression at mRNA and protein levels and UBE2C contributed to the proliferation and colony formation abilities, which were regulated through MALAT1, of lung cancer cells." (PMID 34257576, 2021). "Regarding lung cancers, while approximately all histological subtypes of LUAD tumors showed increased UBE2C expression, the increased level was more statistically significant for lung adenocarcinoma mixed type, followed by lung adenocarcinoma NOS." (PMID 31067633, 2019). "The expression of UBE2C can be downregulated through the knockdown of MALAT1, leading to the inactivation of WNT, PI3K/AKT, and MAPK/ERK, thus inhibiting proliferation, migration, and invasion of lung cancer cells." (PMID 37958776, 2023). "Our data revealed that upregulation of UBE2C and repression of autophagic processes rewired the expression patterns of proliferation marker Ki67, cell cycle enzymes, EMT panels, and apoptosis family members to facilitate the invasive growth of lung cancer." (PMID 29904125, 2018). "UBE2C is not play a crucial role HCC but also in variety of cancers: lung cancer, gastric cancer." (PMID 36882493, 2023). "mTORC signals are negative regulators of autophagy, and UBE2C-mediated autophagy repression contributes to malignant phenotypes of lung cancer cells, suggesting that autophagy modulation via the DEPTOR/mTORC axis could be actively involved in the growth-suppressing effect of UBE2C knockdown as well." (PMID 36548081, 2023). "Moreover, UBE2C and MALAT1 were indicated as targets of miR-491-5p and inhibition of miR-491-5p restored the MALAT1 knockdown-induced inhibition of the progression of lung carcinoma." (PMID 34257576, 2021).